INS (insulin)
Diseases named in the same sentence as INS in open-access papers (continued):
Sharing a sentence is not in itself a finding about the gene and the disease.
diabetes (continued). "Thus, this compelling need brings a sense of urgency to find a cure for diabetes that can not only halt the progression of autoimmunity in T1D and correct multiple immune dysfunctions in T2D, but also overcome the shortage of insulin-producing β-cells." (PMID 32485922, 2020). "Our findings suggest that changes in MCU expression or activity may contribute to defective insulin secretion in some forms of diabetes." (PMID 32350566, 2020). "The main pathogenesis of diabetes is an absolute or relative reduction in insulin secretion." (PMID 33343659, 2020). "Also, in Germany digital solutions including continuous glucose monitoring, smart insulin pens as well as automated insulin delivery systems play an increasing role in diabetes self-management." (PMID 33198734, 2020). "The WHO defines diabetes as a multiple metabolic disorder, characterized by chronic hyperglycemia with impaired metabolism of carbohydrates, fats and proteins, resulting from defects in insulin secretion, insulin action or both." (PMID 32927638, 2020). "In the first cluster, the “Pediatrics” grouping is connected to “Endocrinology and Metabolism,” suggesting that the majority of interventions for children with diabetes and adolescents were concentrated on using medications to enhance metabolic pathways such as insulin infusion or an insulin pump." (PMID 32121642, 2020). "This may be explained by a wider range of insulin status, which influences serum urate levels through renal excretion, in the diabetes participants than in the overall participants." (PMID 32175012, 2020). "Type 1 diabetes mellitus (T1D) is an autoimmune disease in which insulin-producing β-cells within pancreatic islets are destroyed by an autoimmune attack coordinated by autoantigen-specific polyclonal T lymphocytes that have escaped control of immune tolerance." (PMID 32143316, 2020). "In this study, we aimed to evaluate the influence of the residual production of insulin on immune system after the onset of diabetes and if the duration of honeymoon period could be related to the onset of other autoimmune conditions." (PMID 32215008, 2020). "Previous studies have demonstrated that β-cell dysfunction, including insulin secretion and compensatory changes in β-cell mass, is essential for the development of the diabetes phenotype, suggesting that the proliferation of β-cells occurs before the onset of overt hyperglycemia." (PMID 32328034, 2020). "Acute treatment with BAR-1 in pancreatic islets isolated from rats demonstrated significant effects on gene expression, glucose-stimulated insulin secretion and partial anandamide antagonism, conducting to the next in-vivo experiments performed in animal models of prediabetes and diabetes states." (PMID 32132523, 2020). "Out of these, 9 were known diabetics who were controlled on oral hypoglycaemic drugs or insulin." (PMID 33094149, 2020). "This acetone vs. glucose data-sheet can be developed as a handout for patients including different tables that show the respected glucose level based on acetone level under different conditions such as insulin level, gender, age, type of diabetes, time of day (fasting or after food intake)." (PMID 32106464, 2020). "In the last years, several studies have focused on the relationship between adipocyte size and inflammation as well as impaired glucose-insulin homeostasis and diabetes, by demonstrating that increased adipocyte size is associated with a metabolically unfavorable profile in obese individuals." (PMID 33260451, 2020). "Another possible explanation for the inverse association between urate and diabetes is an antioxidant property of urate in the blood since oxidative stress is known to be involved in the pathogenesis of diabetes through development of insulin resistance and deterioration of insulin secretion." (PMID 32175012, 2020). "Interestingly, glucose modulated DBMSC expression of genes involved in insulin secretion and prevention of diabetes." (PMID 32077075, 2020).
diabetes (continued). "Diabetes mellitus is a metabolic disorder disease usually originating from the dysfunction of pancreatic β cells, which could impair insulin target organs (e.g., the liver)." (PMID 31790971, 2020). "One patient had developed diabetes mellitus requiring insulin therapy, and seven (70%) had developed exocrine pancreatic insufficiency, leading to digestive complaints and changes in fecal consistency requiring dietary changes and enzyme replacement therapy at every meal." (PMID 32193697, 2020). "In addition to insulin, the activity of autophagy in diabetes can be modified by other hormonal regulators." (PMID 32340263, 2020). "On the other hand, E. hallii improved insulin sensitivity in a mouse model for diabetes." (PMID 32610452, 2020). "Patients with LEAD at baseline were older, with longer duration of diabetes, and had higher systolic BP, worse renal function, lower total cholesterol, and were more likely to receive insulin, aspirin and statin therapies compared with patients without LEAD at baseline." (PMID 33302958, 2020). "Thus, biologically active insulin analog can be efficiently produced in bacteria and potentially applicable in the treatment of human diabetes." (PMID 31918694, 2020). "We hypothesize that hospitalized insulin-treated diabetes patients with hypertensive crisis have more hypoglycemic episodes than their counterparts without hypertensive crisis on admission." (PMID 33292431, 2020). "This may be attributed to the compounding effects of increasing resistance to insulin and dysfunction of the pancreatic islets with aging, thus diabetes often affects older people more than young people." (PMID 32867822, 2020). "Indeed, observational studies show different associations for SFAs of varying physical, chemical, and metabolic structures, hence supporting different effects of diverse SFAs on blood lipids, glucose-insulin homeostasis, insulin resistance, and diabetes." (PMID 32824377, 2020). "Diabetes mellitus is a group of metabolic diseases characterized by chronic hyperglycemia resulting from defects in insulin secretion, insulin action or both, leading to various serious damaging consequences such as heart attacks, blindness, kidney failure, leg amputation and stroke." (PMID 33081260, 2020). "Therefore, diabetic patients and their families have more problems in this regard,which suggests that health providers should teach patients and relevant medical staff more knowledge of insulin, so as to improve their attitude towards diabetes." (PMID 32576159, 2020). "Diabetes is a metabolic disorder that affects millions of people worldwide and depends on the reduced capacity or the complete failure of the pancreas to produce insulin, possibly combined with the resistance of tissues to insulin action." (PMID 32797106, 2020). "As a secondary hypothesis, plasma norepinephrine concentrations are expected to be elevated both in insulin-treated diabetes patients with hypertensive crisis and in diabetes patients with hypoglycemia on admission." (PMID 33292431, 2020). "Owing to the relationship between BAT, glucose, insulin, and lipids, this work could have implications for the relief of metabolic disorders far beyond diabetes, including atherosclerosis and cardiovascular disease." (PMID 31220223, 2020). "After 3‐months of diabetes, a total of 1,696 (2.6%) of the identified loci were found to have altered methylation compared to age‐matched, non‐diabetic controls with the majority of these (1,389 (81.9%)) normalized by treatment with insulin." (PMID 33200530, 2020). "One of the treatments for this disease is the use of exogenous insulin, especially for patients with Type 1 diabetes mellitus, although insulin may also be required for patients with Type 2 diabetes mellitus." (PMID 33121199, 2020). "Serum levels of adiponectin also correlates with insulin sensitivity in obesity and diabetes." (PMID 33396267, 2020).
diabetes (continued). "Pharmacological therapy and/or insulin may be required in order to maintain the blood glucose level as near as possible to normal and to delay or possibly to prevent the development of diabetes-related health problems." (PMID 32340373, 2020). "The patient had a history of diabetes mellitus treated with insulin, abuse of alcohol and smoking." (PMID 32413773, 2020). "Possible explanations for our results could be that the users of insulin pumps and CGMs might have had more severe forms of diabetes to begin with or that self-adjustment of insulin dosing may be more challenging during pregnancy." (PMID 32488037, 2020). "The classical treatment of diabetes mellitus involves the administration of insulin." (PMID 33167495, 2020). "Oxyntomodulin reduces food intake and increases energy expenditure, leading to significant weight loss in a 28-day clinical study in human volunteers over 28 days, and has been shown to improve insulin secretion in short-term clinical studies in people with diabetes." (PMID 32436022, 2020). "In experimentally induced or diabetes-associated chronic insulin resistance (and hyperinsulinemia), such a protective stress response of the endoplasmic reticulum to high insulin levels is diminished or absent." (PMID 32819363, 2020). "Such mechanistic interaction of proteins could explain the actions of such DRGs in diabetes and how it can modify insulin action on metabolic, cellular, and biological process/and disorders." (PMID 32753925, 2020). "Various researchers have studied the impact of smoking on diabetes and insulin." (PMID 32850233, 2020). "Resistance training combining heavy and explosive loads could improve insulin sensitivity and decrease abdominal fat in elderly people with diabetes." (PMID 32894048, 2020). "Many studies have been done to determine whether isoflavonoids may play any role in reversing the insulin resistant effect in diabetes." (PMID 33255206, 2020). "However, using a FGM system to investigate glycemic control and GV in poorly controlled type 2 diabetes mellitus (T2DM) treated with glucagon-like peptide-1 (GLP-1) analog in combination with continuous subcutaneous insulin infusion (CSII) therapy is rare." (PMID 31859911, 2020). "Through the reduction in proinflammatory mediators directly and indirectly, HO-1 may contribute to improving insulin sensitivity in diabetics, reducing adipogenesis and the probability of CVD development." (PMID 32903449, 2020). "J.B. Collip, a visiting biochemist, joined the group and provided the expertise needed to purify the active glucose-lowering component from the extracts, leading to the first successful test of insulin in a 14-year-old boy with diabetes, Leonard Thompson, in January 1922." (PMID 32396624, 2020). "Moreover, a cross-sectional study demonstrated that diabetes-specific not only directly affects blood sugar but also indirectly affects blood sugar through adherence to insulin and type 2 diabetes treatment." (PMID 32016121, 2020). "Vanadium is a biological trace element that has a function to mimic insulin for diabetes." (PMID 32210760, 2020). "Diabetes mellitus (DM) is a metabolic disorder of multiple etiologies characterized by chronic hyperglycemia with disturbances of carbohydrate, fat, and protein metabolisms resulting from defects in insulin secretion, insulin action, or both." (PMID 33204677, 2020). "Also, the AD-associated insulin signalling impairment in the brain resembles the dysfunction of insulin signalling in the peripheral organs, including the pancreas, adipose tissues, liver, and muscle, in diabetes." (PMID 33379163, 2020). "In experimental and human diabetes, EpCAMpos/MUC6high cell population in PBGs respond to diabetes with proliferation and differentiation toward insulin-producing cells, indicating that PBG niches may rescue pancreatic islet impairment in diabetes." (PMID 32984373, 2020).
diabetes (continued). "Beta cell dysfunction, in relation to insulin secretion, presents as hyperinsulinemia during the adaptive or early pathogenesis of diabetes but evolves to hypoinsulinemia towards beta cell exhaustion and failure in the progression to overt diabetes." (PMID 33158303, 2020). "In the physiological process of diabetes, insulin is secreted from the cell after synthesis." (PMID 32595730, 2020). "Type 2 diabetes mellitus (T2DM) increases the risk of developing AD and AD patients also exhibit disturbed energy metabolism and insulin resistant in the brain, possibly due to impairments of insulin signaling." (PMID 32210760, 2020). "In the prediabetes cohort, beta cell function and insulin sensitivity were related; this was not the case in the diabetes cohort, probably because the capacity to compensate for peripheral insulin resistance by secreting more insulin is greater in prediabetes than once diabetes is manifest." (PMID 32002573, 2020). "Factors that may explain insulin treatment failure, include complex diabetes regime, polypharmacy, side effects, therapeutic inertia and non-adherence." (PMID 32002193, 2020). "However, patients treated with basal insulin presented a higher risk of all-cause mortality than patients treated with TZDs and DPP-4is, especially those who endured long-term diabetes." (PMID 32238842, 2020). "Type 2 diabetes mellitus is a metabolic complex disease caused by several factors that is characterized by relative lack of obesity, insulin, insulin resistance, and high blood sugar." (PMID 32703184, 2020). "Therefore, both defective insulin signaling to NOS and NOS uncoupling in diabetes can lead to abnormal vasomotion and vascular insulin resistance." (PMID 32666009, 2020). "Since the metabolites that we found to be associated with fasting insulin, HOMA-IR and Matsuda Index were mainly overlapping, these measures may reflect similar biological pathways in the development of type 2 diabetes mellitus." (PMID 32124065, 2020). "Alternatively, existing health promotion and universal prevention programs may consider adding diabetes-specific information, such as insulin restriction, given the serious medical complications associated with this behaviour." (PMID 32128205, 2020). "Although diabetes research is at its peak with several new antidiabetic drugs, advanced patient‐specific stem cell transplant/therapy, and insulin therapy, we are yet far from identifying a permanent cure for the “silent killer” (Abdelalim, Bonnefond, Bennaceur‐Griscelli, & Froguel, 2014)." (PMID 32170854, 2020). "Third, the risk of misclassification by excluding patients who might have had other types of diabetes (patients administered insulin for more than 3 months) was reduced." (PMID 32563247, 2020). "Diabetes mellitus is a metabolic disorder depicted by hyperglycemia (elevated levels of blood glucose) and glucose intolerance, which brings about defects of insulin secretion or insulin's action to boost glucose uptake." (PMID 32148647, 2020). "Recently, it has been suggested that dopamine and glucagon-like peptide-1 exert opposing effects on the glucose-stimulated insulin secretion regulatory system and the anti-incretin effect of dopamine have been indicated as a potential mechanism of diabetes remission after bariatric surgery." (PMID 33271740, 2020). "Indeed, transgenic mice overexpressing miR-7a in β-cells develop diabetes due to impaired insulin secretion and β-cell dedifferentiation." (PMID 32182790, 2020). "The majority of patients 36.8% were on insulin for the control of their diabetes." (PMID 32523842, 2020). "With exceeding BMI, patients become more insulin resistant and diabetes may develop when insulin secretion cannot adequately compensate." (PMID 33374430, 2020). "Reduced insulin secretion occurring in diabetes mellitus increases lipolysis." (PMID 32161725, 2020).
diabetes (continued). "Regarding diabetes, Patti et al19 reported a higher risk of stroke or systemic embolism in patients with diabetes receiving insulin treatment compared with those without insulin." (PMID 32293685, 2020). "The latest research shows that SCFAs can not only effectively reduce the incidence of enteritis, cardiovascular disease, colon cancer, obesity and diabetes, but also play an important role in maintaining the balance of energy metabolism (mainly glucose metabolism) and increasing insulin tolerance." (PMID 33194780, 2020). "In our study, insulin use in patients without diabetes is associated with higher morbidity and mortality rates compared to patients with diabetes." (PMID 33118731, 2020). "Diabetes mellitus is a metabolic disorder characterized by chronic hyperglycemia as a result of damage to insulin production (type 1 diabetes mellitus/T1DM) or insulin resistance (type 2 diabetes mellitus/T2DM) and results in abnormal carbohydrate, fat, and protein metabolism." (PMID 32399477, 2020). "The insulin resistance observed in these diabetics could be attributed to excessive lipid metabolites or cytokines inhibiting insulin signal." (PMID 32028922, 2020). "In individuals without diabetes, accentuated day long incremental insulin responses to meals have also been shown to be associated with coronary heart disease." (PMID 32366255, 2020). "Studies on pseudocereals, such as amaranth, showed that its consumption may also reduce the blood serum glucose levels and increase insulin levels in diabetes-induced rats." (PMID 33027944, 2020). "Therefore, thisstudy aimed to investigate the impacts insulin, metformin and pioglitazone as well assuperovulation on the expression profile of Muc1 during the implantationprocess, by using experimental rat diabetes model (type 1 and type 2 diabetes)." (PMID 33098389, 2020). "The low levels of INS are responsible for dyslipidemia in patients with diabetes." (PMID 32425787, 2020). "The expression of mutant insulin may – depending on the type of mutation and the expression level – lead to permanent neonatal DM (now termed mutant INS gene induced diabetes of youth – MIDY, also known as maturity-onset diabetes of the young 10 – MODY10)." (PMID 33029223, 2020). "Indeed, restoring or maintaining the function of residual insulin/glucose-responsive cells prevents the progression of diabetes and reduces medical costs." (PMID 33198288, 2020). "Furthermore, patients with uncontrolled diabetes mellitus had also polyuria increasing the excretion of INS by kidneys and worsening the insulin resistance of patients." (PMID 33153126, 2020). "Additionally, higher blood concentrations of LPC are positively correlated with the muscle insulin sensitivity index in diabetic patients and inversely correlate with impaired fasting glucose and diabetes incidence." (PMID 32599910, 2020). "The positive effect of MNAM on insulin sensitivity in diabetes was abrogated, suggesting that the SIRT1/FOXO1 signal pathway could regulate the effects of MNAM in obese T2DM model." (PMID 32280711, 2020). "Insulin insufficiency in diabetic mellitus patients may actually be the main reasonresponsible for a significant reduction in the activities of liver hexokinase because itsactivity depends on insulin." (PMID 32423242, 2020). "Diabetes mellitus (DM) is a heterogeneous form of metabolic disorder characterized by chronic hyperglycemia with impaired carbohydrate, fat, and protein metabolism due to insulin secretion defects and/or peripheral tissue insulin action." (PMID 32190699, 2020). "After treatment, PANC-1 changed their ultrastructure to that typical of islets-aggregates, showing a significantly increased production of insulin and C peptide, which could be a promising new approach to diabetes treatment." (PMID 32316284, 2020). "Initiation of insulin treatment in patients without previously known diabetes is associated with a need for training in blood glucose measurements and insulin injection." (PMID 32539810, 2020).